CDKN2B (cyclin dependent kinase inhibitor 2B)
Diseases named in the same sentence as CDKN2B in open-access papers (continued):
Sharing a sentence is not in itself a finding about the gene and the disease.
gastric cancer (20 papers, 2012 to 2023). A primary or metastatic malignant neoplasm involving the stomach. "This would adversely affect the expression of KLF2-regulated genes such as CDKN1A and CDKN2B that encode cyclin-dependent kinase inhibitors p21 and p15, respectively, leading to augmented tumorigenesis in gastric cancers." (PMID 36010595, 2022). "CDKN2B has been shown to be associated with the development of colorectal and gastric cancers." (PMID 36536279, 2022). "For example, the TF E2F1 evokes the TINCR transcriptional activity and hastens gastric cancer progression through activating the TINCR/STAU1/CDKN2B axis." (PMID 34721660, 2021). "For instance, lncRNA-TINCR can form TINCR-STAU1 complex to degrade cyclin dependent kinase inhibitor 2B (CDKN2B) mRNA through the SMD pathway in gastric cancer." (PMID 30744670, 2019). "E2F1 could induce TINCR transcriptional activity and accelerated the progression of gastric cancer by activating the TINCR/STAU1/CDKN2B signaling axis." (PMID 32851080, 2020). "It is interesting to note that Jie and colleagues reported that EZH2 substantially impedes CDKN2B activation, which contributes to cellular senescence triggered by EZH2 depletion in gastric cancer cells." (PMID 33664859, 2021). "We also reported that TOB1 overexpression in human gastric cancer (MKN28 and AGS) cells restored the levels of SMAD4 and increased the promoter activity and the mRNA and protein level of its target gene CDKN2B (P15(INK4B)), thereby inducing cell cycle arrest and apoptosis." (PMID 26694352, 2015). "Though the results need to be validated in future studies, our miroarray data have revealed that other key components of cell cycle kinase regulators including TP53INPI and CDKN2B, are deregulated with forced expression of ZIC1 in an individual MKN28 gastric cancer cell line." (PMID 22799764, 2012). "RASSF1A, p14ARF, and MGMT; CHRNA3, DOK1, and GNMT; p16, hMLH1, MINT1, MINT2, MINT12, MINT25, and MINT31; APC, CDH1, MHL1, CDKN2A, CDKN2B, and RUNX3; CDH1; DKK3; PTEN; MGMT; TFPI2; CACNA2D3; PCDH10; SOX2; MAL; and COX2 were previously reported to be hypermethylated in gastric cancer." (PMID 26121593, 2015). "Interestingly, two prototypical Myc-repressed genes, CDKN1B (p27KIP1) and CDKN2B (p15INK4B) 39, 46, 53, 54, showed no response to manipulation of c-Myc in the context of gastric cancer, strengthening the concept that c-Myc regulates gene expression selectively and specifically." (PMID 32292506, 2020).
meningioma (20 papers, 2007 to 2026). A generally slow growing tumor attached to the dura mater. "Loss of NF2 and CDKN2A/CDKN2B is common in higher-grade meningiomas and promotes progression in preclinical models." (PMID 41545592, 2026). "CDKN2A and CDKN2B have been associated with poorer prognosis in meningioma, acute lymphoblastic leukemia and lung adenocarcinoma." (PMID 39236081, 2024). "Alterations of CDKN2A and CDKN2B were found more frequently in recurrent meningiomas and were associated with poor prognosis." (PMID 36661712, 2023). "Homozygous deletions in the cell cycle regulator genes CDKN2A and/or CDKN2B are often found in recurrent and progressive meningiomas and are associated with poor prognosis." (PMID 37675219, 2023). "The last WHO classification (5th Edition, 2021) integrated a TERT promoter mutation or a homozygous deletion of CDKN2A and/or CDKN2B as new criteria for the recognition of grade 3 meningiomas." (PMID 36551712, 2022). "Other recently identified mutations are linked to a phosphatase tensin homolog on chromosome 10 (PTEN), as well as cyclin kinases CDKN2A/CDKN2B, main tumor suppressor genes predominantly implicated in meningioma progression." (PMID 36551712, 2022). "Recurrent genomic alterations, mainly involving CDKN2A/CDKN2B locus loss on 9p, are found frequently in meningiomas at recurrence as well as at progression and are associated with prognosis." (PMID 36230612, 2022). "Losses of cyclin dependent kinase inhibitors, CDKN2A and CDKN2B, have been implicated as the tumor suppressor genes on chromosome 9p responsible for malignant meningioma phenotypes." (PMID 17937814, 2007). "The mutation or deletion of CDKN2A and CDKN2B has been linked to a poorer prognosis in meningioma." (PMID 35712491, 2022). "CDKN2B was associated with malignant pleural mesothelioma, osteosarcoma and meningioma." (PMID 32887258, 2020). "For example, meningiomas with a telomerase reverse transcriptase (TERT) promoter mutation or a homozygous deletion of CDKN2A and/or CDKN2B are classified as WHO grade 3." (PMID 37675219, 2023). "Other genetic mutations have also been reported, including phosphatase and tensin homolog (PTEN), cyclin-dependent kinase inhibitor 2A (CDKN2A), and cyclin-dependent kinase inhibitor 2B (CDKN2B) genes which can be found in grade III meningiomas." (PMID 33014773, 2020). "In summary, this study provided evidence that p14ARF, RASSF1A, p15INK4B (CDKN2B), RUNX3, GATA6, p16INK4A (CDKN2A), NDRG2 and to lesser extent ATM and RARβ promoter methylation are associated with the development of meningiomas." (PMID 25648363, 2015). "The update in 2021 included molecular factors that significantly shorten survival and increase recurrence, such as meningiomas with a telomerase reverse transcriptase (TERT) promoter mutation or homozygous deletions in the cell cycle regulator genes CDKN2A and/or CDKN2B." (PMID 39796674, 2024). "A CDK inhibitor combined with ribociclib could be a potential treatment approach for meningiomas with mutations in the tumor-suppressor genes CDKN2A and CDKN2B (NCT02933736)." (PMID 35712491, 2022). "Moreover, deletions of CDKN2A/CDKN2B are of poor prognostic factors in anaplastic grade III meningiomas." (PMID 34359639, 2021). "In addition to the CDKN2A/CDKN2B genes, the KLF4 (Kruppel like factor 4) gene has also been recently reported to be mutated in meningiomas (particularly among secretory tumors) in association with lack of NF2 mutation." (PMID 25965831, 2015). "In contrast with other chromosomal alterations, the role of chromosome 9 in the development of malignant meningiomas is better defined, since it has been mostly associated with three tumor suppressor genes coded at chromosome 9p21: CDKN2A/p16INKa, CDKN2A/p14ARF and CDKN2B/p15ARF." (PMID 25965831, 2015).
meningioma (continued). "In our study, fibroblastic meningioma was detected with increasing expression of CCND1, CDK6, and E2F3, and decreasing expression of CDKs inhibitors including CDKN1A, CDKN2A, and CDKN2B, suggesting a role of cell cycle deregulation in the tumorigenesis of fibroblastic meningioma." (PMID 23285163, 2012). "Some genetic alterations discovered in higher grade meningioma are deletions on 1p, 6q, 10q, 14q, 9p (CDKNA, p14ARF, CDKN2B) and 18q chromosomes and gains on 1q, 9q, 12q, 15q, 17q, and 20q." (PMID 38279335, 2024). "Alterations on chromosome 9p21 during meningioma progression have been found to induce losses of the tumor suppressor genes CDKN2A (p16INK4a), p14ARF, and CDKN2B (p15INK4b)." (PMID 34359639, 2021). "The aim of this study was to evaluate the methylation status of 12 cancer-related genes, namely ERCC1, hMLH1, ATM, CDKN2B (p15INK4B), p14ARF, CDKN2A (p16INK4A), RASSF1A, RUNX3, GATA6, NDRG2, PTEN, and RARβ, in 44 meningioma samples of WHO grade I and II." (PMID 25648363, 2015). "Atypical and malignant meningiomas have more complex genetic alterations with losses of the G1-S phase cell cycle checkpoint regulators, CDKN2A and CDKN2B, and p14ARF on chromosome 9p contributing to more aggressive meningioma phenotypes." (PMID 17937814, 2007). "Additionally, inactivation through hypermethylation of CpG islands has also been reported in a smaller proportion of meningiomas, including hypermethylation of CDKN2A/p16INKa in 8-17% of cases, CDKN2A/p14ARF in 4-13%, and CDKN2B/p15ARF in 4% of these tumors." (PMID 25965831, 2015). "It has been reported that the majority of anaplastic meningiomas either show homozygous deletions of CDKN2A, p14ARF, and CDKN2B, mutations in CDKN2A and p14ARF, or lack of expression of one or more of these genes." (PMID 23285163, 2012). "Genetic alterations of the Nf2 gene are present in 60% of sporadic meningiomas regardless of grade, suggesting their initiating role in meningeal tumorigenesis; meanwhile, CDKN2A (p16INK4a), p14ARF, and CDKN2B (p15INK4b) are thought to be responsible for progression to higher grades of meningioma." (PMID 39996452, 2025).
acute myeloid leukemia (15 papers, 2007 to 2023). Acute myeloid leukemia (AML) is a group of neoplasms arising from precursor cells committed to the myeloid cell-line differentiation. "In this study methylation Specific Melting Curve Analysis (MS-MCA) and real time PCR was used to assess the CDKN2B promoter hyper-methylation and gene expression in 59 Iranian acute myeloid leukemia (AML) patients." (PMID 29552069, 2017). "Although the methylation of the 5 ́ promoter region of genes, which leads to transcriptional silencing, is the major mechanism of CDKN2B gene inactivation in acute myeloid leukemia (AML), homozygous deletion or intragenic mutation mechanism of CDKN2B inactivation in AML was reported rarely." (PMID 29552069, 2017). "Furthermore, alterations to the interplay between DNA methylation and modifications to H3K4/K27 contribute to the altered expression of the cyclin-dependent kinase inhibitor 2B (CDKN2B or p15) gene observed in acute myeloid leukemia (AML)." (PMID 33172892, 2021). "SUV39H1 inhibition is sufficient for re-expression of the silenced tumor suppressor genes CDKN2B and CDH1 marked by H3K9me3 in acute myeloid leukemia." (PMID 26840455, 2016).
colorectal cancer (15 papers, 2012 to 2025). A primary or metastatic malignant neoplasm that affects the colon or rectum. "Conversely, increased cell proliferation and colorectal cancer cell invasion is mediated by the targeting of the Cyclin-Dependent Kinase inhibitor 2B (CDKN2B) by miR-708, while, in bladder cancer the targeting of Caspase-2 by miR-708 reduces cell apoptosis." (PMID 35011736, 2022). "CCK-8 results revealed that silencing of KLF2 or CDKN2B (P15) partially abolished SNHG1 knockdown induced growth arrest of colorectal cancer cells." (PMID 30266084, 2018). "Consequently, CDKN2B inhibited CDK4/CDK6, inducing cell cycle arrest and cellular senescence, a process linked to colorectal cancer progression." (PMID 40634753, 2025). "Furthermore, PRMT5 functionally interacts with EZH2 to suppress CDKN2B expression through epigenetic mechanisms, promoting colorectal cancer (CRC) progression." (PMID 39043634, 2024). "To investigate whether KLF2 and CDKN2B were involved in the SNHG1 induced promotion of colorectal cancer cell growth, we performed rescue assays." (PMID 30266084, 2018). "The CDKN2B gene is located on chromosome 9p21, a locus at which deletions frequently occur in many primary human tumors, including esophageal carcinoma and colorectal cancer." (PMID 23049694, 2012). "For instance, in a senescence model of colorectal cancer cells, N6-adenosine-methyltransferase 70 kDa subunit (METTL3) was upregulated, leading to N6-methylation of CDKN2B mRNA, which increases its stability, expression and protein levels." (PMID 40634753, 2025). "SNHG1 promotes colorectal cancer cell growth through epigenetic silencing of KLF2 and CDKN2B in the nucleus." (PMID 30266084, 2018). "(f) The relation between CDKN2B and SNHG1 expression analyzed in colorectal cancer samples from TCGA cohort (n = 478, r = − 0.20, P < 0.001)." (PMID 30266084, 2018). "High expression of SNHG1 in patients with colorectal cancer can interact with EZH2 to regulate histone methylation of Krüppel-like factor 2 (KLF2) and cyclin-dependent kinase inhibitor 2B (CDKN2B) in the nucleus and affect the biological behavior of colorectal cancer cells." (PMID 40226409, 2023). "(d) CDKN2B expression was analyzed in colorectal cancer samples and normal samples from TCGA cohort." (PMID 30266084, 2018). "Mechanistic investigations revealed that SNHG1 could exhibit different regulatory mechanisms in the nucleus and cytoplasm, and it could promote the development of colorectal cancer by regulating CCND2, KLF2 and CDKN2B expression." (PMID 30266084, 2018). "Finally, we observed a negative correlation between SNHG1 and KLF2 or CDKN2B expression in colorectal cancer tissues by analyzing RNA sequencing data from TCGA database." (PMID 30266084, 2018).
lung cancer (15 papers, 2010 to 2025). A malignant neoplasm involving the lung. "A recent meta-analysis of lung cancer GWASs by TRICL found rs1333040, which is approximately 74kb upstream from CDKN2B, to be associated with lung cancer (OR = 1.06; P = 9.4×10–5), with a stronger association for SCC (OR = 1.14; P = 2.9×10–7)." (PMID 24681604, 2014). "A third recent study reported that 9p21.3 loss (as assessed by CDKN2A, CDKN2B plus MTAP) was associated with poor survival after anti-PD-1 monotherapy but not in ICT–chemotherapy combination treated patients with nonsquamous lung cancer." (PMID 36395141, 2022). "In lung cancer, patients with co-occurring CDKN2A, CDKN2B and IFN-I cluster deletion display shorter survival as compared with the ones carrying only deletion of CDKN2A." (PMID 40877968, 2025). "ZEB proteins have been shown to protect lung cancer cells from EGFR-induced senescence through their ability to down-regulate CDKN1A and CDKN2B." (PMID 38069026, 2023). "However, considering that the CyclinD1-CDK4/6-Rb pathway is downstream of the EGFR signaling pathway, it is likely that this cell cycle pathway, which involves CDKN2B and RB1, plays an important role in lung cancer progression and/or therapeutic resistance in patients with EGFR active mutation." (PMID 29343775, 2018).
ovarian carcinoma (15 papers, 2012 to 2025). A malignant neoplasm originating from the surface ovarian epithelium. "We found that a low expression level of CDKN2B and WNT11 was associated with longer survival in ovarian cancer patients, while high expression levels of SMAD3, ZFYVE16, BMP6, LEFTY1, and DVL2 were significantly associated with poor survival." (PMID 38403634, 2024). "The ratio of genomic alterations in CDKN2A and CDKN2B was also high in endometrial and ovarian cancers." (PMID 38201563, 2023). "Knock down of SMYD3 in ovarian cancer tissues leads to upregulation of CDKN2B (p15INK4B), CDKN2A (p16INK4), CDC25A and CDKN3 as members of cyclin-dependent kinase inhibitors (CDK)." (PMID 33333978, 2020). "In ovarian cancer, aberrant methylation of CpG islands in tumor suppressor genes, including CDKN2B, BRCA1, APC, RASSF1, and CDH13, is a frequent event compared to that in the normal ovarian surface epithelium." (PMID 31615043, 2019). "In the GBM data, the involved pathways include parts of the RB signaling and RTK signaling pathways (CDKN2B, CDK4; EGFR, NF1 ), and in the ovarian carcinoma data a recurrent mutated module related to cell cycle and DNA repair (CCNE1, MYC, RAD52 ) is revealed." (PMID 24565034, 2013). "CDKN2B is a cell cycle control gene and several lines of evidence indicate that variants of these genes, particularly CDKN2A, are crucial in ovarian cancer." (PMID 23226780, 2012). "Our results indicate that the CDKN2B gene is silenced in ovarian cancer, and especially in clear cell carcinoma, by promoter methylation instead of deletion or mutation." (PMID 23226780, 2012). "Our data indicate that methylation of the CDKN2B gene is a frequent event in ovarian carcinogenesis and that analysis of only three genes is sufficient to detect the presence of methylation in 35% of ovarian cancer cases." (PMID 23226780, 2012). "Finally, a recent study clarified that SMARCA4 T910M contributes to the targeting of SWI/SNF complexes on chromatin in ovarian carcinoma cells and that could influence CDKN2B expression." (PMID 31996670, 2020). "However, certain investigators have also suggested that CDKN2B does not have an important role in ovarian carcinogenesis, due to the absence of mutations and homozygous deletion of the gene in ovarian cancer." (PMID 23226780, 2012). "In fact, CpG islands in tumor suppressor genes such as CDKN2B, BRACA1, RASSF1A, MLH1, RARB2, and TIMP3 undergo aberrant methylation in ovarian cancer." (PMID 31615043, 2019). "For example, CDKN2B and CDK4 as well as EGFR and NF1 are involved in the RB and RTK signaling pathways, respectively and the CCNE1, MYC and RAD52 module in ovarian carcinoma is involved in cell cycle." (PMID 24565034, 2013). "A large number of putative suppressor genes that are silenced or activated by aberrant methylation have been identified in ovarian cancer, including hypermethylation of OPCML, RASSF1, CDKN2B as well as classical tumor suppressors BRCA1, p16 and MLH1, and hypomethylation of LINE-1, SLC6A12 and PRAME." (PMID 35710397, 2022). "In contrast to CDKN2A, the methylation and mRNA expression of CDKN2B in ovarian cancer have not been extensively investigated." (PMID 23226780, 2012).
sarcoma (15 papers, 2014 to 2025). A usually aggressive malignant neoplasm of the soft tissue or bone. "In fact, reduced expression of CDKN2A (a tumor suppressor protein similar to CDKN2B), has been observed in sarcoma progression and correlated with reduced patient survival." (PMID 29383146, 2017). "Notably, copy numbers (CNs) for cyclin-dependent kinase inhibitor (CDKN) 2A (CDKN2A) and CDKN2B in the sarcoma tissue were 0.6 and 0.5, respectively." (PMID 40416963, 2025). "In addition, a large-scale study of 77 radiotherapy-induced sarcomas reported a higher frequency of c-MYC amplification and losses of CDKN2A and CDKN2B in radiotherapy-induced sarcomas than in sporadic sarcomas." (PMID 41007286, 2025).